ADAM32 (ADAM metallopeptidase domain 32)
Description:
May play a role in sperm development and fertilization This is a non-catalytic metalloprotease-like protein.
Tractability: Antibody: UniProt predicts a signal peptide or a membrane-spanning region; its Gene Ontology location is reachable by antibodies, with medium confidence.
Gene: Protein-coding gene on chromosome 8 (39,106,990 to 39,284,917, forward strand). Ensembl gene ENSG00000197140.
Subcellular location: Membrane
Subcellular location (Human Protein Atlas): Principal piece
Gene Ontology:
Molecular function: protein binding; metalloendopeptidase activity; metallopeptidase activity
Biological process: binding of sperm to zona pellucida; cell adhesion; male gonad development; proteolysis
Cellular component: sperm principal piece; plasma membrane; cell surface; membrane
Genetic constraint (gnomAD): Loss-of-function variants: 48 observed, 58.64 expected, observed/expected ratio (o/e) 0.82, 90% interval 0.65 to 1.04. The upper end of that interval is the gene's LOEUF score, 1.04, which puts it in group 4 of 6, group 1 being the genes least tolerant of losing a copy. Missense variants: 618 observed, 618.13 expected, observed/expected ratio (o/e) 1, 90% interval 0.94 to 1.07. Synonymous variants: 218 observed, 209.97 expected, observed/expected ratio (o/e) 1.04, 90% interval 0.93 to 1.16.
Homologues: Orthologues: chimpanzee ADAM32 (99% identical), mouse Adam32 (57% identical), rat Adam32 (56% identical), pig ADAM32 (52% identical), zebrafish adam9b (26% identical), Caenorhabditis elegans unc-71 (23% identical), zebrafish adam10a (17% identical), Drosophila melanogaster mmd (17% identical), zebrafish adam10b (14% identical), Drosophila melanogaster kuz (13% identical), Caenorhabditis elegans sup-17 (13% identical). Paralogues in human: ADAM2 (38% identical), ADAM18 (38% identical), ADAM9 (30% identical), ADAM30 (26% identical), ADAM20 (25% identical), ADAM29 (25% identical), ADAM21 (24% identical), ADAM12 (24% identical), ADAM22 (24% identical), ADAM15 (24% identical), ADAM19 (24% identical), ADAM28 (24% identical), and 8 more.
Diseases named in the same sentence as ADAM32 in open-access papers:
ADAM32 is named in the same sentence as 13 diseases in open-access papers, as found by Europe PMC text mining. Sharing a sentence is not in itself a finding about the gene and the disease. The quoted sentences say what the papers report.
hepatoblastoma (4 papers, 2022 to 2025). Hepatoblastoma (HB) is a malignant hepatic tumor and is the most common pediatric liver cancer. "The downregulated gene Adam32 is positively correlated with the occurrence of hepatoblastoma, and it is known to promote cancer stem cell and epithelial mesenchymal transformation and induce cancer." (PMID 38891594, 2024). "Abnormally high expression of ADAM32 was recently observed in hepatoblastoma; experiments in HepG2 and primary hepatoblastoma cells showed that colony formation, cell migration and invasion, and cell viability were increased upon overexpression of ADAM32 and decreased upon knockdown." (PMID 39050735, 2024). "And among these, ADAM32 is highly expressed in hepatoblastoma (HBL) and plays an important role in oncogenic properties." (PMID 40507253, 2025).
breast carcinoma (1 paper, 2022). "Similar oncogenic functions of ADAM32 in HBL and HBCs were observed in experiments using breast cancer cell line MCF7." (PMID 36230656, 2022). "First, evaluation of cell viability with the MTT assay demonstrated that ADAM32 could increase cell viability in the HBL, HBCs, and breast cancer cell lines evaluated by forced expression and knockdown experiments." (PMID 36230656, 2022). "Forced expression and knockdown experiments directed at ADAM32 in the HBL cell line HepG2, primary cells of HBL (HBCs), and the breast cancer cell line MCF7 were performed to clarify its biological functions because prognostic importance of ADAM32 has been observed in breast cancer." (PMID 36230656, 2022).
Dyskinesia (1 paper, 2021). A movement disorder which consists of effects including diminished voluntary movements and the presence of involuntary movements. "ADAM32 (Hoehn and Yahr), IRAK3 (dyskinesia), LMAN1 (UPDRS part 2), and RHD (dyskinesia) passed MR-Egger intercept, Cochran’s Q and I2 tests." (PMID 34930919, 2021).
hepatocellular carcinoma (1 paper, 2022). A malignant tumor that arises from hepatocytes. "One possible mechanism of oncogenic expression of ADAM32 that has been reported is a gain of chromosome 8 (where ADAM32 is located) in cases of HBL, but not in hepatocellular carcinoma (HCC)." (PMID 36230656, 2022).
lung carcinoma (1 paper, 2025). "On the other hand, expression levels of ADAM32 remained unchanged in HUH-6 and lung cancer cell lines, although an increase in CA9 expression was observed." (PMID 40507253, 2025). "In order to elucidate the regulatory mechanisms of ADAM32 under hypoxic conditions, the HBL cell line as well as breast and lung cancer cell lines were utilized." (PMID 40507253, 2025). "Therefore, we decided to study the regulatory mechanisms of ADAM32 under hypoxic conditions by using HBL, breast, and lung cancer cell lines." (PMID 40507253, 2025). "Methods/Results: When these cells were exposed to 1% O2 (hypoxia), it was found that the levels of ADAM32 increased at 48 h in HepG2, MCF7, and MDA-MB-231 but not in HUH-6 or lung cancer lines." (PMID 40507253, 2025).
oligospermia (1 paper, 2017). Decreased number of spermatozoa in the semen. "Eight genes among 817 genes (0.01%) (ADAM32, DYNLRB2, KLHL10, RIMBP3C, SEPT12, TIMD4, TSACC and TTC25) were common between MArrest and teratospermia, and three genes among 435 genes (0.007%) (HRASLS, LIMS3 and MRPL42) were common between oligospermia and teratospermia." (PMID 29150651, 2017).
cancer (8 papers, 2016 to 2025). A tumor composed of atypical neoplastic, often pleomorphic cells that invade other tissues. "The SCNA comprised focal losses in 8p11.22 including the metallopeptidase genes ADAM18 and ADAM32 in 22% of lFL (q = 1.4E-15) and focal gains affecting 11q24.3 harboring cancer-associated genes ETS1 and FLI1 in 22% of lFL (q = 2E-27)." (PMID 37563306, 2023). "Despite mounting evidence for the pivotal role of m6A modification in cancer biology, its potential role in regulating ADAM32 expression under hypoxic conditions remains to be elucidated." (PMID 40507253, 2025). "To investigate this, we examined ADAM32 expression under hypoxic conditions and found that while its levels increased in some cancer cell lines, including HBL, the response varied between different cell types." (PMID 40507253, 2025). "Of particular note is ADAM32, which has attracted attention due to its upregulation in various cancers, including HBL." (PMID 40507253, 2025). "We found low expression of the disintegrin and metalloproteinase families of the genes ADAM11 and ADAM32, which have relevance in cancer." (PMID 37047231, 2023). "We demonstrated for the first time that ADAM32 plays a crucial role in HBL via regulation of cancer cell proliferation, stemness, migration, invasion, and acquired resistance to therapy via an extrinsic apoptotic signal." (PMID 36230656, 2022). "Quantitative RT-PCR demonstrated an association between ADAM32 expression and the expression of genes related to cancer stem cells and epithelial–mesenchymal transition (EMT), suggesting a role of ADAM32 in cancer stemness and EMT." (PMID 36230656, 2022). "Notably, the modulation of ADAM32 expression has been shown to sensitize HBL cells to CDDP, while its upregulation has been associated with increased cell motility and cancer stemness." (PMID 40507253, 2025). "Given that several ADAM family members are upregulated under hypoxic conditions in various cancers, we hypothesized that the tumor microenvironment plays a role in ADAM32 regulation." (PMID 40507253, 2025). "In this study, we demonstrate that the expression level of ADAM32 is particularly high in HBL tissue samples and is associated with poor prognosis in various cancer types through the regulation of cancer cell proliferation, stemness, migration, invasion, and acquired resistance to chemotherapy." (PMID 36230656, 2022). "According to our data, we speculate that like many of the ADAMs, ADAM32 may have importance in cancer cell proliferation and progression." (PMID 27391163, 2016). "Therefore, ADAM32 may play a role in cancer stem cell phenotypes." (PMID 36230656, 2022).
tumor (8 papers, 2016 to 2025). "Alcohol intake was also positively associated with DMR.A6 related to the gene ADAM32, which encodes a protein involved in diverse biological processes, such as brain development, fertilization, tumor development, and inflammation." (PMID 30940212, 2019). "Microarray analysis revealed that IGF2BP1 and IGF2BP2, both known to stabilize mRNA, were upregulated in HBL tumor samples, and their expression correlated with ADAM32 levels." (PMID 40507253, 2025). "This suggests that intrinsic differences in tumor subtypes may influence ADAM32 regulation in response to hypoxia." (PMID 40507253, 2025). "Our previous studies have shown that ADAM32 expression is high and plays a crucial oncogenic role in HBL, driving tumor cell proliferation, migration, and resistance to chemotherapy." (PMID 40507253, 2025). "In cases with PLEKHA5 and FRS2 rearrangements that were multi-sampled, the respective fusions were present in all investigated tumour materials (core needle biopsy, resection specimen, recurrence and/or metastasis), except for Case 12 (FRS2::ADAM32)." (PMID 39322633, 2024). "Lastly, the methylation analysis revealed that ADAM11, ADAM32, and ADAM33 exhibited higher levels of methylation in tumor tissues compared to normal tissues." (PMID 39346916, 2024). "In the cDNA microarray dataset analyzed with GEO2R, expression levels of ADAM32, ADAMTS6, and ADAM9 in HBL tumor tissues were 1.5-fold higher than in NCL." (PMID 36230656, 2022).
infection (1 paper, 2013). The state of being infected such as from the introduction of a foreign agent such as serum, vaccine, antigenic substance or organism. "An important characteristic in DHV is liver injury, and the down-regulated expression of ADAM32 may be associated with the host reduce infection lesion." (PMID 23923051, 2013).
ADAM32 also shares sentences with these, for which no sentence is quoted: gastric cancer (1 paper); leiomyoma (1); leiomyosarcoma (1); teratospermia (1).